ELP2 (elongator acetyltransferase complex subunit 2)
Description:
Component of the elongator complex which is required for multiple tRNA modifications, including mcm5U (5-methoxycarbonylmethyl uridine), mcm5s2U (5-methoxycarbonylmethyl-2-thiouridine), and ncm5U (5-carbamoylmethyl uridine). The elongator complex catalyzes the formation of carboxymethyluridine in the wobble base at position 34 in tRNAs.
Synonyms: STATIP1; FLJ10879; StIP; MRT58; SHINC-2
Tractability: Small molecule: a structure with a bound ligand is known. PROTAC: ubiquitination databases record sites on it; its protein half-life has been measured.
Gene: Protein-coding gene on chromosome 18 (36,129,444 to 36,180,557, forward strand). Ensembl gene ENSG00000134759.
Subcellular location: Cytoplasm; Nucleus
Subcellular location (Human Protein Atlas): Cytosol; Nucleoplasm
Pathways (Reactome):
Chromatin organization: HATs acetylate histones
Gene Ontology:
Molecular function: RNA polymerase II complex binding; protein kinase binding
Biological process: regulation of transcription by RNA polymerase II; regulation of translation; transcription elongation by RNA polymerase II; tRNA wobble uridine modification
Cellular component: cytoplasm; cytosol; elongator holoenzyme complex; nucleoplasm; nucleus; transcription elongation factor complex
Genetic constraint (gnomAD): Loss-of-function variants: 66 observed, 93.24 expected, observed/expected ratio (o/e) 0.71, 90% interval 0.58 to 0.87. The upper end of that interval is the gene's LOEUF score, 0.87, which puts it in group 3 of 6, group 1 being the genes least tolerant of losing a copy. Missense variants: 766 observed, 836.01 expected, observed/expected ratio (o/e) 0.92, 90% interval 0.86 to 0.97. Synonymous variants: 291 observed, 291.04 expected, observed/expected ratio (o/e) 1, 90% interval 0.91 to 1.1.
Homologues: Orthologues: chimpanzee ELP2 (99% identical), macaque ELP2 (98% identical), pig ELP2 (90% identical), rabbit ELP2 (89% identical), dog ELP2 (86% identical), mouse Elp2 (79% identical), guinea pig ELP2 (76% identical), rat Elp2 (71% identical), tropical clawed frog elp2 (61% identical), zebrafish elp2 (57% identical), Drosophila melanogaster Elp2 (41% identical), Caenorhabditis elegans elpc-2 (29% identical).
Diseases named in the same sentence as ELP2 in open-access papers:
ELP2 is named in the same sentence as 22 diseases in open-access papers, as found by Europe PMC text mining. Sharing a sentence is not in itself a finding about the gene and the disease. The quoted sentences say what the papers report.
Intellectual disability (4 papers, 2017 to 2023). "Patients who are compound heterozygotes for two different ELP2 missense mutations demonstrate a lack of motor control starting in early development, severe intellectual disability, and progressive loss of locomotor function." (PMID 31213517, 2019). "Variants in the ELP2 gene are associated with neurodevelopmental (including intellectual) disability while ELP3 variants are associated with ALS, and loss of ELP4 can cause Rolandic epilepsy syndrome and intellectual disability." (PMID 28167615, 2017). "Notably, intellectual disability has also been linked to mutations in the genes of several further enzymes responsible for tRNA modification, including genes modifying the wobble position, such as ADAT3, NSUN2, and ELP2 (the elongator acetyltransferase complex subunit 2)." (PMID 32630140, 2020).
microcephaly (4 papers, 2021 to 2023). A congenital or acquired developmental disorder in which the circumference of the head is smaller than normal for the person's age and sex. "Brain imaging and tractography analysis of the Elp2 mutants revealed microcephaly, loss of white matter tract integrity and an aberrant functional connectome." (PMID 36448458, 2023). "The modelled biallelic point mutations in the ELP2, ELP4 and ELP6 genes originated from patients with intellectual disability, microcephaly, motor impairment, myelination defects and epilepsy." (PMID 36448458, 2023). "In summary, the Elp2 mutant mice recapitulated the clinical features of the patients, including developmental delay with microcephaly, repetitive behavior, and abnormal motor and vocal characteristics." (PMID 33976153, 2021). "However, in contrast to Elp2 mutant animals, no signs of microcephaly and no defects in myelination and development of cortical projection neurons and interneurons have been identified in Elp6L118W mice." (PMID 35698786, 2022).
amyotrophic lateral sclerosis (3 papers, 2017 to 2021). Amyotrophic lateral sclerosis (ALS) is a neurodegenerative disease characterized by progressive muscular paralysis reflecting degeneration of motor neurons in the primary motor cortex, corticospinal tracts, brainstem and spinal cord. "Interestingly, three other Elongator subunits, ELP2 to ELP4, have each been associated with CNS disorders: ELP2 and ELP4 have been implicated in intellectual development disorders and epilepsy, and ELP3 with amyotrophic lateral sclerosis." (PMID 28167615, 2017).
autism spectrum disorder (1 paper, 2024). A spectrum of developmental disorders that includes autism, and Asperger syndrome. "Moreover, ELP2 mutations have been detected in patients with ID and autism spectrum disorder." (PMID 38550277, 2024).
developmental delay (1 paper, 2021). "In this work, we identify six patients presenting with a range of features including global developmental delay, ID, ASD, and drug-resistant epilepsy with ELP2 genetic variants." (PMID 33976153, 2021).
neurodevelopmental disability (1 paper, 2019). "ELP2 mutations were reported as the causative mutations in a familial form of neurodevelopmental disability." (PMID 31213517, 2019).
ovarian carcinoma (1 paper, 2022). A malignant neoplasm originating from the surface ovarian epithelium. "ISG15, SNCA, RIPK2, PLCG2, RHOU, TRIB2 and ELP2 influenced the OS and PFI of ovarian cancer patients in the TCGA-OV dataset, while RIPK2 also affected the OS and PFI of ovarian cancer patients treated with Taxol in the GSE30161, GSE32062 and GSE63885 datasets." (PMID 35477477, 2022).
infection (1 paper, 2022). The state of being infected such as from the introduction of a foreign agent such as serum, vaccine, antigenic substance or organism. "ELP2 gene can rapidly respond to the immune response after Pst DC3000 infection in Arabidopsis." (PMID 35585486, 2022).
tumor (1 paper, 2022). "However, the ELP1 construct also remains in the tumor for a prolonged period, while the ELP2 construct not only shows less initial accumulation, but also a much more rapid clearance from the tumor." (PMID 35684309, 2022). "We have previously shown that the thermoresponsive ELP1 accumulates in the tumor much more rapidly than the non-thermoresponsive ELP2." (PMID 35684309, 2022). "With tumors thus less exposed to doxorubicin delivered with an ELP2 rather than an ELP1, the less efficient tumor reduction seen with an ELP2 carrier is unsurprising." (PMID 35684309, 2022).
ELP2 also shares sentences with these, for which no sentence is quoted: cancer (4 papers); autism (1); chronic myeloid leukemia (1); epilepsy (1); hepatocellular carcinoma (1); hypertrophic cardiomyopathy (1); leprosy (1); leukemia (1); neurologic diseases (1); Parkinson disease (1); rheumatoid arthritis (1); Rolandic epilepsy (1); serous ovarian cancer (1).